EGFR (epidermal growth factor receptor)
Diseases named in the same sentence as EGFR in open-access papers (continued):
Sharing a sentence is not in itself a finding about the gene and the disease.
lung adenocarcinoma (continued). "This supports previous work demonstrating that in areas with high prevalence of EGFR mutation, the performance of the LENT score can be improved by re-scoring lung adenocarcinomas from the highest to the lowest risk category (EGFR-LENT)." (PMID 40524925, 2025). "An integrated model combining clinical variables, radiomic features, and deep learning was developed to predict EGFR mutation status in patients with lung adenocarcinoma based on pretreatment 18F‐FDG PET/CT imaging." (PMID 41263395, 2025). "ROC curve analysis was performed to evaluate the ability of SII to predict ACM in patients with stages IIIB–IV EGFR-mutated lung adenocarcinoma." (PMID 41268168, 2025). "The limitations of this work are that the HCC827 cell line was derived from a lung adenocarcinoma with EGFR mutation and high sensitivity to TKIs, which prevents us from generalizing the results to other cancer types and tumor microenvironments." (PMID 40507826, 2025). "Univariate analysis of the effects of EGFR 19, 21 mutation on radiological features of invasive lung adenocarcinoma." (PMID 41378298, 2025). "In summary, logistic regression and decision tree models constructed using age, lymphadenopathy, pleural thickening, and brain metastasis show promise for noninvasive prediction of EGFR 19Del and 21L858R mutation subtypes in lung adenocarcinoma." (PMID 41049833, 2025). "Recent research showed that the lung adenocarcinoma with solid subtype had a lower EGFR mutation rate." (PMID 40182027, 2025). "Incorporation of targeted therapies such as inhibitors of epidermal growth factor receptor (EGFR) or vascular endothelial growth factor (VEGF) signaling have improved outcomes in human lung adenocarcinoma harboring sensitizing mutations." (PMID 40969344, 2025). "Herein, we present for the first time a case of advanced lung adenocarcinoma with a novel METex14 skipping mutation following resistance to EGFR-TKI and subsequent sensitivity to savolitinib." (PMID 40129940, 2025). "We report the first case of tumor-to-tumor metastasis from EGFR-mutated lung adenocarcinoma to a meningioma occurring 14 years after curative lobectomy." (PMID 41416296, 2025). "Non-invasive prediction of EGFR mutation status in lung adenocarcinoma (LUAD) is critical for treatment planning, particularly in small pulmonary nodules where tissue genotyping is limited." (PMID 41417019, 2025). "In this research, the EGFR mutation rate was significantly related to the histological subtypes of lung adenocarcinoma (P=0.0003)." (PMID 40182027, 2025). "The presence of activating epidermal growth factor receptor (EGFR) mutations sensitive to EGFR tyrosine kinase inhibitors (TKIs) was originally noted in lung adenocarcinoma patients." (PMID 40076686, 2025). "This study highlights the potential of integrating clinical, radiomic, and deep learning features as a noninvasive approach for accurately predicting EGFR mutation status in lung adenocarcinoma." (PMID 41263395, 2025). "used stacked generalization to combine PET and CT imaging information, improving the AUC for predicting EGFR mutation status in lung adenocarcinoma patients from 0.72 and 0.74 (single-modality models) to 0.84 (combined PET/CT model)." (PMID 41395623, 2025). "This article reports a case of an advanced lung adenocarcinoma patient with EGFR mutation, who developed abnormal vaginal bleeding after EGFR-TKIs treatment failure, and biopsy confirmed endometrial metastasis." (PMID 40935645, 2025). "Epidermal growth factor receptor (EGFR) tyrosine kinase inhibitors (TKIs) are indicated for advanced lung adenocarcinoma patients harboring susceptible EGFR mutations." (PMID 40999598, 2025).
lung adenocarcinoma (continued). "In our study of 317 patients with EGFR-mutated lung adenocarcinoma, we demonstrated that high baseline PD-L1 expression (TPS ≥50%) was significantly associated with both shorter PFS and OS." (PMID 41446744, 2025). "Among 208 patients with GGO-associated lung adenocarcinoma, 121 (58.17%) had wild-type EGFR, while 87 (41.83%) had mutated EGFR." (PMID 41020204, 2025). "With rapid advances in immunotherapies and precision medicine, the role of epidermal growth factor receptor (EGFR) mutations in lung adenocarcinoma has become increasingly recognized." (PMID 41268168, 2025). "Consistently, B7-H3 deletion has been shown to reduce the phosphorylation levels of AKT and the signal transducer and activator of transcription 3 (STAT3) while increasing susceptibility to EGFR tyrosine kinase inhibitors in lung adenocarcinoma cells." (PMID 40004194, 2025). "Based on these findings, the patient was initiated on combination therapy with osimertinib, carboplatin, and pemetrexed for metastatic EGFR-mutated lung adenocarcinoma." (PMID 40656425, 2025). "BRAF mutations occur in approximately 2–4% of patients with lung adenocarcinoma and are mutually exclusive of EGFR, KRAS, and EML4–ALK." (PMID 39995841, 2025). "This study aimed to evaluate the predictive performance of integrated clinical and CT-based radiomic models for assessing targeted therapy efficacy in advanced lung adenocarcinoma patients with EGFR (epidermal growth factor receptor) mutations." (PMID 40520794, 2025). "By constructing a predictive model, we seek to establish a noninvasive approach for precise EGFR mutation profiling in lung adenocarcinoma." (PMID 41244899, 2025). "In this retrospective study, we assessed baseline PD-L1 tumor proportion score (TPS) in a large real-world cohort of patients with EGFR-mutated stage III–IV lung adenocarcinoma treated with first-line osimertinib." (PMID 41446744, 2025). "Many studies have demonstrated that the therapeutic efficacy of 1st and 2nd generation TKIs is restricted in patients with lung SCC and lung adenocarcinoma that contains EGFR KDD mutations." (PMID 40918464, 2025). "We found that the overexpression of IFI6 under the influence of the AHSA1-HSP90AA1 complex significantly enhances Osimertinib resistance in EGFR-mutated lung adenocarcinoma cells." (PMID 40234395, 2025). "The female lung adenocarcinoma patient (concurrent EGFR mutations and DCTN1–ALK fusion) with brain metastases developed resistance to chemotherapy or targeted therapy." (PMID 41246301, 2025). "We report a 52‐year‐old man with longstanding PNH who developed stage IVA epidermal growth factor receptor‐mutated lung adenocarcinoma." (PMID 40827190, 2025). "Case 1: A 63‐year‐old man with lung adenocarcinoma harboring an EGFR L861R mutation (cStage IVB) received afatinib 40 mg/day." (PMID 41350121, 2025). "Patients with lung adenocarcinoma (LUAD) harboring EGFR mutations other than exon 19 deletions (19del) and L858R had received insufficient attention, and their treatment options remained limited with suboptimal outcomes." (PMID 41162774, 2025). "The EGFR gene, which encodes a transmembrane tyrosine kinase, is a commonly mutated gene in lung adenocarcinoma and is more frequently observed in elderly patients (≥60 years old), with a mutation rate of approximately 15%–50%." (PMID 41020204, 2025). "Overall, this case presentation highlights the diagnostic and therapeutic complexity of synchronous multiple primary lung adenocarcinomas with discordant EGFR mutations." (PMID 40855618, 2025). "This study highlights the critical role of tertiary lymphoid structures (TLSs) as a prognostic indicator associated with disease-free survival (DFS) in early-stage EGFR-mutant lung adenocarcinoma." (PMID 40723259, 2025).
lung adenocarcinoma (continued). "Summary of EGFR-mutated lung adenocarcinoma cases with pancreatic metastasis registered in the Center for Cancer Genomics and Advanced Therapeutics database as of April 16, 2025." (PMID 40656425, 2025). "Lung adenocarcinoma (LUAD) is driven by epidermal growth factor receptor (EGFR) mutations, making it a key therapeutic target." (PMID 40429751, 2025). "Although subject to certain limitations, this study revealed the value of SII in independently predicting stages IIIB–IV EGFR-mutated lung adenocarcinoma." (PMID 41268168, 2025). "Herein, we report a case of an EGFR-mutated lung adenocarcinoma patient who developed refractory dyspnea and hypoxemia after 1.5 months of osimertinib therapy, ultimately leading to treatment failure and death." (PMID 40538542, 2025). "During the data collection phase, case selection is restricted to pathologically confirmed lung adenocarcinoma patients with EGFR mutations (exon 19 deletions or L858R substitutions) verified by molecular testing." (PMID 40708937, 2025). "Herein, we present the case of a patient with stage IV lung adenocarcinoma with an EGFR L858R mutation, who developed peritoneal metastasis involving the small intestine, leading to intestinal obstruction and death following osimertinib resistance." (PMID 40432924, 2025). "This case underscores the complex diagnostic and therapeutic challenges posed by the coexistence of TB and EGFR-mutated lung adenocarcinoma." (PMID 41141063, 2025). "This study demonstrates that a deep learning model based on 18F‐FDG PET/CT imaging holds significant potential for predicting EGFR mutation status in patients with lung adenocarcinoma." (PMID 41263395, 2025). "EGFR mutation is a prominent driver in lung adenocarcinoma and serves as a primary target for targeted therapies." (PMID 39843434, 2025). "In advanced lung adenocarcinoma, particularly in cases harboring epidermal growth factor receptor (EGFR) gene mutations, EGFR tyrosine kinase inhibitors (EGFR-TKIs) are the standard first-line therapy." (PMID 40827190, 2025). "The therapeutic potential of dose-escalated EGFR-TKIs in high-risk EGFR-mutant lung adenocarcinoma patients remains underexplored." (PMID 41479790, 2025). "In line with data already available from previously published studies, EGFR mutation is also a common finding in patients with lung adenocarcinoma, especially among women, and the exon 19 deletion is the most common variation." (PMID 40104451, 2025). "In women, the predominant histological subtype is lung adenocarcinoma, commonly associated with epidermal growth factor receptor (EGFR) mutations, and EGFR-tyrosine kinase inhibitors (EGFR-TKIs) can significantly improve patient prognosis." (PMID 40935645, 2025). "This research highlights a case of advanced lung adenocarcinoma accompanied by meningeal metastasis, characterized by the presence of the EGFR L858R mutation." (PMID 40696624, 2025). "In this retrospective study, we analyzed 317 patients with EGFR-mutated stage III–IV lung adenocarcinoma treated with first-line osimertinib." (PMID 41446744, 2025). "Prior research highlights differences between the biological traits of T-SCLC and primary SCLC or EGFR-mutated lung adenocarcinoma (LUAD)." (PMID 40437627, 2025). "Studies demonstrate that growth in nodule size and solid components correlates strongly with EGFR mutations, with EGFR-mutated patients exhibiting more complex imaging findings like higher rates of vacuole or honeycomb signs in lung adenocarcinoma." (PMID 41312067, 2025). "Epidermal growth factor receptor (EGFR) mutations are observed in approximately 20% of lung adenocarcinomas, with higher prevalence among Asian patients, reaching nearly 50%." (PMID 40165604, 2025).
lung adenocarcinoma (continued). "Conversely, the mRNA level of DUSP13B was downregulated in lung adenocarcinoma tissues with EGFR mutations (P = 0.025)." (PMID 39721017, 2025). "In conclusion, our study provides real-world clinical evidence that high baseline PD-L1 expression is an adverse prognostic factor in patients with advanced EGFR-mutated lung adenocarcinoma receiving first-line osimertinib therapy." (PMID 41446744, 2025). "A substantial proportion of lung adenocarcinomas harbor activating mutations in the epidermal growth factor receptor (EGFR)." (PMID 40538542, 2025). "Epidermal growth factor receptor (EGFR)-positive lung adenocarcinoma refers to tumors harboring activating EGFR mutations and are typically treated with EGFR-directed tyrosine kinase inhibitors." (PMID 41542005, 2025). "Clarifying EGFR mutation status provides crucial guidance for initiating and selecting therapeutic strategies in lung adenocarcinoma." (PMID 41244899, 2025). "This study presents a noninvasive, interpretable random forest model that integrates CT radiomics, CTR, and selected clinical variables to predict EGFR mutation status in small (≤ 3 cm) lung adenocarcinoma nodules." (PMID 41417019, 2025). "In lung adenocarcinoma, mutations of the EGFR or KRAS gene represent the most common oncogenic drivers." (PMID 40227775, 2025). "Pathological examination of the pleural fluid led to a diagnosis of stage IVA EGFR-mutated lung adenocarcinoma." (PMID 40827190, 2025). "One of the most frequently observed genetic mutations in lung adenocarcinoma is in the EGFR gene, which codes for a transmembrane receptor tyrosine kinase." (PMID 40182027, 2025). "This phenomenon is most commonly observed in some epidermal growth factor receptor (EGFR)-mutated lung adenocarcinoma patients who develop resistance to EGFR inhibitors, after which their tumors transform into SCLC." (PMID 41194225, 2025). "In lung adenocarcinoma, patients with obesity showed a lower prevalence of EGFR and a higher prevalence of KRAS mutations." (PMID 40149286, 2025). "The results revealed that the expression rate of SHH protein exhibited a substantial increase in lung adenocarcinoma tissues with EGFR gene mutations (P = 0.012; 83.8%)." (PMID 39721017, 2025). "Case presentation: We present a case of a patient with a rare EGFR variant lung adenocarcinoma, who was misdiagnosed using a SGT." (PMID 40218192, 2025). "A retrospective study showed that first‐generation EGFR‐TKIs were less effective for EGFR‐mutated squamous cell lung carcinoma than for lung adenocarcinoma." (PMID 40620186, 2025). "Although osimertinib and afatinib have anti‐tumor efficacy against EGFR L861R‐positive lung adenocarcinoma, we should investigate the efficacy of EGFR‐TKIs in EGFR L861 mutation‐positive cases using a large number of cases." (PMID 41350121, 2025). "Case 2: An 83‐year‐old man with lung adenocarcinoma harboring an EGFR L861R mutation (cStage IVB) received osimertinib 80 mg/day." (PMID 41350121, 2025). "For suspected lung adenocarcinoma cases undergoing spectral CT, the model provides real-time EGFR mutation probability scoring during initial radiological evaluation." (PMID 41244899, 2025). "This study included 626 patients with early-stage lung adenocarcinoma who underwent surgical resection between October 2017 and December 2023.EGFR and ALK mutations were analyzed postoperatively." (PMID 41378298, 2025). "We report a case of advanced lung adenocarcinoma with EGFR-sensitive mutation that transformed into small cell lung cancer after EGFR-TKIs treatment." (PMID 39995840, 2025).
lung adenocarcinoma (continued). "Our study, which represents the largest cohort to date using the 22C3 assay, provides a more robust estimate of the prevalence of high baseline PD-L1 expression in EGFR-mutated lung adenocarcinoma within real-world clinical practice." (PMID 41446744, 2025). "Prior to the advent of radiomics, the prediction of EGFR mutation status in lung adenocarcinoma predominantly relied on clinical characteristics." (PMID 40708937, 2025). "Here, we present a case of lung adenocarcinoma harboring an EGFR (EGFR) mutation that transformed into squamous cell carcinoma." (PMID 40792216, 2025). "Common mutation types in lung adenocarcinoma include epidermal growth factor receptor (EGFR), anaplastic lymphoma kinase (ALK) rearranged, and C-ros oncogene 1-receptor tyrosine kinase (ROS1) fusion." (PMID 40134592, 2025). "In individuals with lung adenocarcinoma, epidermal growth factor receptor (EGFR) gene mutations are common, and EGFR-tyrosine kinase inhibitors (EGFR-TKIs), a class of targeted molecular therapies, are widely used in clinical practice." (PMID 39754212, 2025). "Nowadays, the correlation between molecular changes and morphology characteristics of lung adenocarcinoma has attracted the research interests greatly, especially the EGFR mutations." (PMID 40182027, 2025). "Smoking history, tumor size, tumor subtype, rhabdomyoid differentiation and extracellular mucus were related to EGFR mutations in lung adenocarcinoma." (PMID 40182027, 2025). "By analyzing the relationship between SII and ACM in patients with stages IIIB–IV EGFR-mutated lung adenocarcinoma, this study aims to provide a foundation for developing a prognostic tool to guide individualized treatment." (PMID 41268168, 2025). "While this study sheds light on the potential benefits of AICT for patients with EGFR‐mutated lung adenocarcinoma, it comes with several limitations that must be acknowledged." (PMID 40289745, 2025). "A PDX model was established from an advanced‐stage EGFR‐mutated (L858R+T790M+MET amplification) lung adenocarcinoma patient that had progressed following resistance to both 2nd generation TKI (afatinib) and 3rd generation TKI (osimertinib)." (PMID 40521789, 2025). "This case report describes a patient with IVa stage advanced lung adenocarcinoma with multiple intrapulmonary metastases carrying an epidermal growth factor receptor (EGFR) exon 19 deletion mutation." (PMID 40959071, 2025). "In this study, we analyzed lung adenocarcinoma specimens harboring EGFR mutations from patients who responded to first- or second-generation EGFR-TKI monotherapy." (PMID 40259053, 2025). "A study in Korea found that 183 (39%) of 477 lung adenocarcinoma patients had EGFR mutations, and 100 (21%) had TB lesions." (PMID 40347011, 2025). "Further investigation into the mechanisms driving resistance to Osimertinib is necessary to address the restricted treatment options and survival advantages that are compromised by resistance in patients with EGFR-mutated lung adenocarcinoma (LUAD)." (PMID 39773749, 2025). "A 69‐year‐old woman with advanced‐stage EGFR mutation‐positive lung adenocarcinoma developed persistent diarrhoea 3 weeks after starting osimertinib, complicated by anorexia, hypotension, anaemia and renal failure requiring hospitalisation." (PMID 40641492, 2025). "This retrospective study included 106 EGFR-mutated advanced lung adenocarcinoma patients treated with targeted therapies at the Second Hospital of Jilin University (2020–2023)." (PMID 40520794, 2025). "A non-smoking 48-year-old man presented with clinical stage IVB (cT1bN0M1c) lung adenocarcinoma harboring an EGFR L858R mutation, along with diffuse bone metastases in the trunk and proximal limbs and cancerous pleurisy." (PMID 40104434, 2025).